BMP10 (bone morphogenetic protein 10)
Diseases named in the same sentence as BMP10 in open-access papers (continued):
Sharing a sentence is not in itself a finding about the gene and the disease.
basal cell carcinoma (2 papers, 2013 to 2015). A carcinoma involving the basal cells.
breast tumor (2 papers, 2018 to 2023). "A recent literature review has highlighted that BMP2 enhanced angiogenesis through endothelial cells, whilst BMP9 and BMP10 inhibited cell growth and tumour angiogenesis in breast tumours." (PMID 37333824, 2023). "Our results rather support that BMP10 does not play an important role in this breast tumor model." (PMID 30165893, 2018).
liver disease (2 papers, 2020 to 2021). "We assessed BMP9, BMP10 and soluble endoglin (sEng) levels and their relationships to liver disease severity and associated pulmonary vascular syndromes in a cohort of well-characterised liver disease patients." (PMID 32454407, 2020). "Owing to the variability in the reported levels of apelin peptides in liver disease patients, we have used this method to extract apelin from plasma samples from the same cohort in which BMP9 and BMP10 were measured and quantified apelin levels by ELISA." (PMID 33171278, 2021). "In conclusion, we show that advanced liver disease leads to reductions in the expression of BMP9 and BMP10 in the liver leading to reduced plasma levels and activity on endothelial cells." (PMID 32454407, 2020). "Therefore, the aim of the present study was to investigate the plasma levels of BMP9, BMP10 and sEng in a well-characterised cohort of patients with liver disease to assess whether the levels of these ligands change and if they segregate with disease severity or pulmonary vascular complications." (PMID 32454407, 2020). "However, we have found that the decrease in plasma apelin occurs at an earlier stage of liver disease than for BMP9 and BMP10 suggesting that if BMPR-II signalling is impaired this is not mediated via loss of these receptor ligands." (PMID 33171278, 2021). "During the preparation of this manuscript, a letter reported reductions of plasma BMP9 in patients with HPS or PoPH compared to liver disease patients without these syndromes, whereas BMP10 levels were only reduced in HPS." (PMID 32454407, 2020). "Plasma samples from patients with liver disease (n = 83) and non-disease controls (n = 21) were assayed for BMP9, BMP10 and sEng." (PMID 32454407, 2020).
liver fibrosis (2 papers, 2023 to 2024). "Pdgfb expression was significantly upregulated in KCs and ECs after Gdf2 and Bmp10 deletion, ultimately leading to HSCs activation and liver fibrosis." (PMID 39453386, 2024). "Thus, the correlation between Gdf2/Bmp10 expression and liver fibrosis needs further investigation." (PMID 39453386, 2024).
myocardial infarction (2 papers, 2019 to 2020). Gross necrosis of the myocardium, as a result of interruption of the blood supply to the area, as in coronary thrombosis. "A study in a rat model of myocardial infarction suggested that exogenous BMP10 administration may stimulate cardiomyocyte cell cycle reentry." (PMID 31620450, 2019). "Experiments in a non-reperfused mouse model of myocardial infarction showed a 2-fold increase in BMP10 levels 21 days after coronary occlusion." (PMID 31620450, 2019).
portopulmonary hypertension (2 papers, 2021 to 2023). "This is consistent with reports of reduced circulating BMP9 and BMP10 levels in portopulmonary hypertension patients." (PMID 33834622, 2021).
prostate carcinoma (2 papers, 2017 to 2020). A carcinoma that arises from epithelial cells of the prostate gland. "Recently, BMP9 and BMP10 signaling were linked to NOTCH signaling, one of the major pathways involved in prostate cancer development, progression and bone metastasis." (PMID 29259971, 2017). "In order to understand the role of BMP9 in prostate cancer progression, we employed the soluble chimeric protein ALK1Fc (ACE-041) which binds BMP9 and BMP10 with high affinity and blocks their signaling via ALK1 and ALK2 receptors by acting as a ligand trap." (PMID 29259971, 2017).
Telangiectasia (2 papers, 2023). Telangiectasias refer to small dilated blood vessels located near the surface of the skin or mucous membranes, measuring between 0.5 and 1 millimeter in diameter. "For instance, the inhibition of BMP10 by high doses of Sotatercept can interfere with BMP10 homeostatic function on the endothelium, maybe resulting in telangiectasias." (PMID 37595264, 2023). "Of note, the Q26X homozygous child was diagnosed with PAH at 3 years of age and telangiectasias at 10 years, but BMP9 and BMP10 levels were only measured at 10 years." (PMID 36259599, 2023). "We suggest that the telangiectasias documented in homozygous GDF2 variant carriers lacking BMP9 in our earlier study may reflect the additional loss of circulating BMP10." (PMID 36259599, 2023).
acute respiratory distress syndrome (1 paper, 2023). Progressive and life-threatening pulmonary distress in the absence of an underlying pulmonary condition, usually following major trauma or surgery. "Given that COVID‐19 is a cause of acute respiratory distress syndrome (ARDS), we investigated circulating concentrations of BMP9 and prodomain‐BMP10 (pBMP10) in a cohort of patients with COVID‐19." (PMID 36721385, 2023).
anemia (1 paper, 2023). A reduction in the number of red blood cells, the amount of hemoglobin, and/or the volume of packed red blood cells. "Complete blood count exhibited significant reductions in hemoglobin levels, red blood cell (RBC) counts, and hematocrit levels, indicating anemia in Bmp10-iKO and Bmp9/10-dKO mice." (PMID 36348215, 2023). "Anemia phenotypes were observed in both Bmp10-iKO and Bmp9/10-dKO mice." (PMID 36348215, 2023). "Supplementation of BMP10 protein alleviated anemia and heart phenotypes." (PMID 36348215, 2023).
congenital heart disease (1 paper, 2024). "Early research suggested that bone morphogenetic protein 10 (BMP10) is primarily involved in cardiac development and congenital heart disease processes." (PMID 38760897, 2024).
diabetes (1 paper, 2024). "However, there have been no reports of any reviews discussing the role of BMP10 in diabetes and cardiovascular disease." (PMID 38760897, 2024).
diabetic cardiomyopathy (1 paper, 2024). Diabetic cardiomyopathy is a disorder of the heart muscle in people with diabetes. "This review summarizes the research results of BMP10 in cardiac development, endothelial function and cardiovascular disease in an effort to generate new ideas for future research into diabetic cardiomyopathy." (PMID 38760897, 2024).
endothelial dysfunction (1 paper, 2024). In vascular diseases, endothelial dysfunction is a systemic pathological state of the endothelium (the inner lining of blood vessels) and can be broadly defined as an imbalance between vasodilating and vasoconstricting substances produced by (or acting on) the endothelium. "In recent years, reports have emphasized the effects of BMP10 on myocardial apoptosis, fibrosis and immune response, as well as its synergistic effects with BMP9 in vascular endothelium and role in endothelial dysfunction." (PMID 38760897, 2024).
glioma (1 paper, 2021). A benign or malignant brain and spinal cord tumor that arises from glial cells (astrocytes, oligodendrocytes, ependymal cells). "Furthermore, upon stimulation with TGF-β1, BMP-4, or BMP-10, their levels remained unaltered in T98G glioma cells." (PMID 33471197, 2021).
leukemia (1 paper, 2025). A malignant (clonal) hematologic disorder, involving hematopoietic stem cells and characterized by the presence of primitive or atypical myeloid or lymphoid cells in the bone marrow and the blood. "We observed BMP9 and BMP10 mRNA, highly expressed in K562 and Jurkat leukemia cells, to be undetectable in both control fibroblasts and exp‐CAF2 cells." (PMID 40644310, 2025).
liver cirrhosis (1 paper, 2024). "Given that GDF2 and BMP10 regulated the expression of Gata4 in murine ECs, it is possible that the reduced expression of GATA4 may be due to low expression of GDF2 and BMP10 in liver cirrhosis." (PMID 39453386, 2024).
peripheral nerve injury (1 paper, 2024). Injury to a peripheral nerve. "Taken together, these results suggest that the BMP10/ALK2/Smad1 axis plays a key role in pain hypersensitivity after peripheral nerve injury, which points to its stimulative ability to astrocyte." (PMID 39188955, 2024).
Splenomegaly (1 paper, 2025). Abnormal increased size of the spleen. "However, loss of BMP10 and treatment with anti-BMP9 did cause splenomegaly." (PMID 41222740, 2025).
tumor (12 papers, 2016 to 2026). "Notably, BMP10 overexpression or rBMP10 supplementation effectively mitigated the tumor-promoting effects of METTL3-deficient HSCs." (PMID 42030359, 2026). "Mechanistically, METTL3 deficiency reduced m6A modification and expression of bone morphogenetic protein 10 (BMP10), a known tumor suppressor." (PMID 42030359, 2026). "The genes repressed in both GE1-HCC and GE2-HCC included those with supposed tumour-inhibiting activity, e.g. CXCL14, CCBE1, IGFBP1, RND3, BMP10 and COLEC10, which encode proteins involved in extracellular matrix remodelling, migration and the immune response." (PMID 33541355, 2021). "A second and very interesting challenge is to dissect the effects of both circulating BMP9 and BMP10 proteins in the context of tumor angiogenesis." (PMID 34771575, 2021). "Our studies show that targeting BMP9 or BMP10 differently affect tumor growth, angiogenesis and metastatic dissemination." (PMID 30165893, 2018). "Together these results demonstrate, for the first time, that BMP9 and BMP10 exhibit distinct roles in tumor growth, angiogenesis and metastatic dissemination." (PMID 30165893, 2018). "Since both ALK1’s ligands, BMP9 and BMP10 circulate in blood, there is an urgent need to understand the respective contribution of each ligand in tumor development and metastasis." (PMID 30165893, 2018). "Little is known about the respective roles of BMP9 and BMP10 in tumor angiogenesis, cancer development and metastatic dissemination." (PMID 30165893, 2018). "In these studies, BMP9 and BMP10 were described as tumor suppressors acting directly on cancer cells but their roles in tumor angiogenesis have not been investigated." (PMID 30165893, 2018). "We have previously reported that both ALK1-Fc and ENG-Fc fusion proteins selectively bind BMP9 and BMP10 and display single agent anti-angiogenic and anti-tumor effects in mouse models." (PMID 27248821, 2016). "PTPRS-STAT3 axis mediated in tumor suppressor function of bone morphologic protein-10 (BMP-10)." (PMID 35991009, 2022). "As we will review in the following sections, BMP10 seems to have different effects on tumor angiogenesis than BMP9 and BMP10 may explain the discrepancies observed between ALK1 targeting and direct BMP9 inhibition." (PMID 34771575, 2021). "Interestingly, similar to ALK1-Fc protein, soluble endoglin-Fc was found to bind selectively to BMP9/BMP10 and to effectively inhibit both angiogenesis and tumor xenograft growth in vivo." (PMID 27248821, 2016). "We found that loss of BMP10 did not significantly modify tumor volume." (PMID 30165893, 2018). "For example, BMP10, but not BMP9, is essential for cardiac development, whereas BMP9, but not BMP10, dampens tumour vessel growth." (PMID 36250069, 2022). "This absence of redundancy could be due to differences between physiological and tumor angiogenesis or due to the fact that the role of BMP9 and BMP10 might be different in newborns and adults." (PMID 30165893, 2018). "This supports that, in contrast to post-natal model of angiogenesis or vascular remodeling, there is no redundancy between BMP9 and BMP10 in this tumor context." (PMID 30165893, 2018). "Altogether, our data show that in a tumor environment BMP9 and BMP10 play different roles and thus blocking their shared receptor ALK1 is maybe not appropriate." (PMID 30165893, 2018). "The roles of BMP9 and BMP10 have also been studied in different cancers using tumor cells overexpressing either BMP9 or BMP10, although BMP9 and BMP10 are not or moderately expressed in most of the tumors that have been studied so far." (PMID 30165893, 2018). "In contrast, in our studies of pathological tumor angiogenesis, we did not observe a compensatory increase in expression of BMP10 (or the close family member GDF5) within tumor lysates." (PMID 27741515, 2016). "Indeed, BMP9, but not BMP10, acts as a quiescence factor on tumor growth, lung metastasis and vessel normalization." (PMID 30165893, 2018).
tumor (continued). "We next analyzed tumor vascularization but could not detect any differences in tumor vessel density (podocalyxin staining), nor in vessel perfusion (lectin injection) between CTL and Bmp10-deleted mice." (PMID 30165893, 2018).
cancer (8 papers, 2014 to 2025). A tumor composed of atypical neoplastic, often pleomorphic cells that invade other tissues. "Downregulation of BMP‐10 has been linked to cancer onset and progression, whereas its overexpression limits metastasis and prolongs survival." (PMID 39921464, 2025). "Dysregulated BMP‐10 signaling contributes to cardiovascular diseases and cancer, highlighting the need to control ALK1‐mediated endothelial responses to BMP‐10 for therapeutic development." (PMID 39921464, 2025). "Activin receptor-like kinase 1 (ALK1)-mediated endothelial cell signalling in response to bone morphogenetic protein 9 (BMP9) and BMP10 is of significant importance in cardiovascular disease and cancer." (PMID 32238803, 2020). "Our findings may inform the development of new therapeutics for BMP‐10‐associated diseases like HHT and cancer." (PMID 39921464, 2025). "Gaining a better understanding of the molecular requirements for BMP‐10 activity may lead to improved therapeutic approaches for cancer and vascular diseases." (PMID 39921464, 2025). "Thus, BMP10 administration could be a potential approach to alleviate DOX-induced cardiac injury in patients with cancer." (PMID 35293279, 2022). "Functional pathway of “Molecular Mechanism of Cancer” was indirectly influenced by activated NFKBIA, bone morphogenetic protein 10 (BMP10), RB transcriptional corepressor like 2 (RBL2) and RELA." (PMID 39342193, 2024).
infection (1 paper, 2017). The state of being infected such as from the introduction of a foreign agent such as serum, vaccine, antigenic substance or organism. "Only 3 genes each in the spleen (B2m, Lst1 and Edf1) and the brain (Six6, Cd163 and Bmp10) were modulated at all three time points after V3034 infection." (PMID 28446152, 2017).
inflammation (1 paper, 2017). Aberrant reaction of the microcirculation characterized by movement of fluid and leukocytes from the blood into extravascular tissues. "Taken together, these data reveal that both BMP9 and BMP10 synergize with TNFα to up-regulate endothelial-expressed molecules involved in leukocyte recruitment, in addition to BMP2, a factor previously implicated in endothelial inflammation." (PMID 28646109, 2017).
vascular disorder (1 paper, 2012). A general term used to describe any disease affecting blood vessels]. "Endoglin and ALK1, a TGFβ family type I receptor, show high affinity for BMP9 and BMP10, and are both associated with the inherited vascular disorder Hereditary Haemorrhagic telangiectasia (HHT)." (PMID 22745736, 2012).
BMP10 also shares sentences with these, for which no sentence is quoted: cardiovascular disease (4 papers); ischemic stroke (3); Arrhythmia (2); cardiomyopathy (2); Ventricular hypertrophy (2); Anxiety (1); aortic valve disease (1); arteriovenous malformation (1); cardioembolic stroke (1); Duchenne muscular dystrophy (1); heart disease (1); hepatopulmonary syndrome (1); high output heart failure (1); hypertrophy (1); juvenile polyposis (1); mitral valve regurgitation (1); multiple myeloma (1); neuropathic pain (1); Sepsis (1).